KLHL26 (kelch like family member 26)
Description:
May play a role in endo(sarco)plasmic reticulum (ER/SR) mitochondrial signaling. May be part of the ubiquitin-proteasome system (UPS) and affect ubiquitination and degradation of target substrates in cardiomyocytes.
Tractability: Small molecule: it belongs to a druggable protein family. PROTAC: ubiquitination databases record sites on it.
Gene: Protein-coding gene on chromosome 19 (18,637,025 to 18,671,721, forward strand). Ensembl gene ENSG00000167487.
Gene Ontology:
Molecular function: protein binding; ubiquitin-like ligase-substrate adaptor activity
Biological process: proteasome-mediated ubiquitin-dependent protein catabolic process
Cellular component: Cul3-RING ubiquitin ligase complex
Genetic constraint (gnomAD): Loss-of-function variants: 6 observed, 11.1 expected, observed/expected ratio (o/e) 0.54, 90% interval 0.29 to 1.07. The synonymous counts are far from expectation, so gnomAD's model fits this gene poorly and the ratio says little. Missense variants: 892 observed, 861.56 expected, observed/expected ratio (o/e) 1.04, 90% interval 0.98 to 1.09. Synonymous variants: 464 observed, 389.06 expected, observed/expected ratio (o/e) 1.19, 90% interval 1.11 to 1.29.
Homologues: Orthologues: chimpanzee KLHL26 (100% identical), macaque KLHL26 (97% identical), pig KLHL26 (95% identical), guinea pig KLHL26 (95% identical), dog KLHL26 (92% identical), rat Klhl26 (86% identical), mouse Klhl26 (85% identical), tropical clawed frog klhl26 (79% identical), zebrafish klhl26 (75% identical). Paralogues in human: KLHL13 (41% identical), KLHL9 (41% identical), KLHL31 (33% identical), KLHL36 (32% identical), KLHL14 (31% identical), KLHL22 (30% identical), KLHL32 (29% identical), KLHL20 (28% identical), KLHL5 (28% identical), KLHL1 (28% identical), KLHL34 (28% identical), KLHL4 (27% identical), and 42 more.
Diseases named in the same sentence as KLHL26 in open-access papers:
KLHL26 is named in the same sentence as 3 diseases in open-access papers, as found by Europe PMC text mining. Sharing a sentence is not in itself a finding about the gene and the disease. The quoted sentences say what the papers report.
Ebstein anomaly (2 papers, 2020 to 2024). Ebstein's malformation is a rare congenital cardiac anomaly characterized by rotational displacement of the septal and inferior leaflets of the tricuspid valve such that they are hinged within the right ventricle, rather than as expected at the atrioventricular junction. "The MYH7 has been identified as the strongest genetic link to bothsporadic and familial cases of this disease, however associations with othergenes such as TPM1, Kelch like family member 26 (KLHL26), FLNA orNKX2-5 are also related to Ebstein’s anomaly, albeit with lesssupporting data." (PMID 39077344, 2024).
ovarian carcinoma (1 paper, 2012). A malignant neoplasm originating from the surface ovarian epithelium. "Regarding Klhl26, its function is currently unknown, but it was found mutated in head and neck squamous cell or ovarian carcinomas." (PMID 22761580, 2012).
KLHL26 also shares sentences with these, for which no sentence is quoted: oligodendroglioma (1 paper).